ERBB2 (erb-b2 receptor tyrosine kinase 2)
Diseases named in the same sentence as ERBB2 in open-access papers (continued):
Sharing a sentence is not in itself a finding about the gene and the disease.
tumor (continued). "These tumor cells were first of all analysed for ERBB2 membrane expression by FACS analysis with 97.6% of tumor cells positive for ERBB2-conjugated antibody (R&S, FAB 11299) (data not shown)." (PMID 26133490, 2015). "HER-2, also referred to as c-erbB-2, is a type of oncogene with an homologous sequence with the virus oncogene as well as the oncogene of epidermal growth factor receptor (EGFR), and is overexpressed in various types of tumor." (PMID 25780431, 2015). "Although distinct, BL tumours can be considered an aggressive subgroup of TN cancers, and both are characterised by a lack of oestrogen receptor and c-erbB2 (Her2) expression, limiting systemic treatment options." (PMID 25887320, 2015). "Mechanistically, conditional knockout of E2F3 in mammary epithelial cells diminished the average percentage of cells within ERBB2 tumors undergoing S phase, but this deletion had no impact on tumor growth rates." (PMID 26512919, 2015). "In this study, the ALDH+ CSC population was found to be a prognostic indicator for high tumor grade, negative ER/PR status, ERBB2 overexpression, and expression of basal-like cytokeratins." (PMID 26932376, 2014). "For both the tumour and non-malignant samples, the epithelial cells showed ErbB2-IR whereas stroma did not." (PMID 25215939, 2014). "ErbB2-IR was measured in a well-characterised tissue microarray of tumour and non-malignant samples obtained at diagnosis." (PMID 25215939, 2014). "Experiments using ABD-fusions to an ERBB2-specific Affibody molecule have demonstrated a dramatic decrease in kidney accumulation, an effectively prolonged half-life and an improved tumor accumulation compared to non-fused controls." (PMID 25089830, 2014). "The evidence of a functional role for Nedd9 in ErbB2-dependent tumourigenesis has been provided by the analysis of MMTV-ErbB2 mice with the genetic deletion of NEDD9, demonstrating that MMTV-ErbB2;Nedd9-null mice are strongly resistant to tumour formation." (PMID 25606587, 2014). "Interestingly, our data on exosomal protein profiles from treated Caco-2 showed an enrichment of upregulated proteins involved in tumor etiopathogenesis, including CRC (CD59, CRP, CTSD, HMMR, LY6K, TRIM22), and in cell cycle control (BRAF, CDC2, ERBB2)." (PMID 25594007, 2014). "Those authors also reported an interaction between AR-IR and ErbB2-IR with respect to the tumour stage, but not the Gleason score." (PMID 25215939, 2014). "In contrast to the total block in PyMT induced tumorigenesis, mammary epithelial deletion of β1 integrin in an MMTV/Neu (activated ErbB2) mouse model did not totally prevent tumor development." (PMID 25012362, 2014). "rV-neuT immune serum was able to mediate ADCC, inhibition of SALTO cells proliferation, down regulation of the ErbB2/Neu receptor, inhibition of ERK1/2 phosphorylation and induction of apoptosis, thus suggesting potential mechanisms of in vivo tumor growth interference." (PMID 24886178, 2014). "Its activation might be promoted by tumor-intrinsic mechanisms mediated by receptor tyrosine kinases, such as HER2/erbB2 or induced by its principle activator IFN-γ produced by immune cells." (PMID 24725474, 2014). "Porcine relaxin increased microglia accumulation and invasion of each of the tumour cell lines investigated in this model, independent of the species of origin as well as of erbB2 and hormone receptor expression." (PMID 23963762, 2014). "In vivo studies with murine mammary gland directed overexpression of MMTV-ErbB2/Neu and MMTV-TGFβ or constitutive active mutant TGFβR show that activation of TGFβ signaling pathway enhances ErbB2-induced tumor growth and metastasis to lungs, which can otherwise be a rather slow process." (PMID 24709902, 2014). "We also identify a compact set of gene changes upon ErbB2 inhibition and demonstrate strong overlap with EGFR-driven cancers and further identify PHLDA1 as a novel negative feedback inhibitor and candidate tumor suppressor in ErbB2-dependent cancers." (PMID 25238247, 2014).
tumor (continued). "In the present study, we did not observe ErbB2-IR in the stroma, and the number (with % in parentheses) of cases with ErbB2-IR scores ≥3 were 196/222 (88%), 39/222 (18%) and 201/357 (56%) for non-malignant basal, luminal and tumour samples, respectively." (PMID 25215939, 2014). "The ER+ tumor group had high levels of expression o genes characterized as the luminal profile, including GATA3, an stained with antibodies against luminal cell keratins 5/6 and 17, or were in the group that had high expression of ERBB2 and related genes." (PMID 23599813, 2013). "Histology and immunohistochemistry (IHC) assays revealed that treatment with MM-121 or trastuzumab alone did not alter tumor cell morphology and the expression of erbB2/erbB3 receptors." (PMID 24215614, 2013). "Therefore, microsatellite analysis was performed in all tumor specimens using six couples of primers targeting the 17q21 amplicon, containing TOP2A and ERBB2 genes, and 3p24 and 20q12–q13.1 loci, containing respectively TOP2B and TOP1 genes." (PMID 24216996, 2013). "Furthermore, at the smaller-genomic scale level, ALK fusion-positive tumours were less amplified at the loci containing EGFR family genes, 7p11.2 (EGFR), 17q12 (ERBB2) and other loci, 1p34.3 (MYCL), 7p21.1, 8q24.21 (MYC), 16p13.3 and 17q25.1." (PMID 23289484, 2013). "Collectively, these data demonstrate that the Wnt signaling-active subset of mammary cells does not evolve into tumor following activation of ErbB2." (PMID 24265712, 2013). "Our findings indicate that high expression of LOXL2 promotes tumor-like phenotype in normal mammary cells and suggest that LOXL2 may be used as a marker to identify patients most likely to respond to anti-ErbB2 therapy." (PMID 23971878, 2013). "HER2 protein expression is very high in mouse MMTV-neu2/ErbB2 (ErbB2TG) tumours but not expressed at all in the Wnt10bLacZ tumours." (PMID 23307470, 2013). "The immunophenotypic features of the present patient’s tumor indicated a noticeably different pattern, being ER+, PR+ and ErbB2-negative." (PMID 24137399, 2013). "Mounting evidence indicates that ErbB4, unlike EGFR or ErbB2, functions as a tumor suppressor in many human malignancies." (PMID 24791013, 2013). "To avoid the selection for FAK-proficient ErbB2 tumour epithelia through escape of Cre-mediated recombination, we next intercrossed the FAK conditional mice with a separate MMTV-driven ErbB2 strain that co-expressed ErbB2 and Cre recombinase on the same transcriptional unit." (PMID 22373082, 2012). "ErbB2 negative tumours expressed more LOC643714 mRNA than ErbB2 positive tumours (p = 0.04), which was not unexpected because the majority of the ErbB2 negative tumours was ER positive." (PMID 23270421, 2012). "Although these data demonstrate that FAK activation is involved in the induction and maintenance of ErbB2 tumours, our studies with the MMTV-NIC model indicate that ErbB2 tumours completely lacking FAK can develop eventually." (PMID 22373082, 2012). "NEU/HER2 is the rat homolog of human ERBB2 and in one transgenic mouse model, MMTV-NEU-NT, that expresses the activated mutant form of NEU under the transcriptional control of the MMTV promoter, the mice develop spontaneous tumours in the mammary gland." (PMID 22621282, 2012). "In fact we observed a decrease of both phospho-EGFR and phospho-ErbB2 (not shown) in ErbB2 tumor cells upon treatment with AG1478." (PMID 23028720, 2012). "From the tumor-biology point of view, it is not known why a subset of tumors develops ERBB2 amplification." (PMID 23181561, 2012).
tumor (continued). "Given the dramatic impact of FAK deletion on PyVmT tumour induction, we evaluated whether deletion of FAK in an activated ErbB2 mouse model resulted in a comparable phenotype." (PMID 22373082, 2012). "In contrast, tumor cells at IF lost their polar orientation and displayed fibroblast-like shape, and were negative for ErbB2 expression." (PMID 23133563, 2012). "From these results, we hypothesize that MUC4 inhibition induces expression of TGF-β1 at the mRNA level to create a loop of regulation (feedback) that would result in up-regulation of ErbB2 or MUC4 and promote tumour cell proliferation." (PMID 22393391, 2012). "But there was lack of correlation between low mRNA levels of TOX3 and LOC643714 and high expression of Ki67 and low mRNA level of LOC643714 and negative ErbB2 status of the tumour as well as high histograde." (PMID 23270421, 2012). "The tumours positive and negative for ER, PR and HER2 showed a significantly different level of expression for their respective genes ESR1, PGR and ERBB2 (P<0.01, Welch's t-test)." (PMID 22067903, 2011). "The cellular models that were used for this study are the only well-established IBC cellular models available; SUM149, an ErbB1 activated, triple-negative (ErbB2-, ER- and PR-) cell line and SUM190, an ErbB2 overexpressed, ER- cell line, both of which have been derived from primary IBC tumours." (PMID 21505458, 2011). "The fact that only 2/13 of the mammary cancers expressed ERBB2/neu/HER2 indicates that STAT1's tumor-suppressing effect is not limited to ERBB2/neu/HER2-induced tumorigenesis." (PMID 22185785, 2011). "Tumor growth inhibition induced by a single dose of AST1306 in the SK-OV-3 xenograft model was accompanied by a rapid (within 2 h) and sustained (≥24 h) inhibition of both EGFR and ErbB2, consistent with an irreversible inhibition mechanism." (PMID 21789172, 2011). "Of these, tumours that are ER/PR negative include the more aggressive basal-like and ERBB2 (HER2)+ tumours." (PMID 21695211, 2011). "Overexpression of the putative tumor suppressor miR-125b, which is underexpressed in DCIS, repressed the expression of MEMO1, which is required for ErbB2-driven cell motility (also a target of miR-125b), and NRIP1/RIP140, which modulates the transcriptional activity of the estrogen receptor." (PMID 21375733, 2011). "Samples that stained positive for ER, PR and HER2 resulted in DASL mRNA average transcript fold changes in ESR1, PGR and ERBB2 (95% CI) of 4.46 (2.01–6.90), 3.41 (1.24–5.58) and 3.59 (1.40–5.77) greater than their respective IHC-negative tumours." (PMID 22067903, 2011). "Analysis of ErbB2-intiated tumors revealed no major effect of increased circulating IGF-I on tumor type (solid adenocarcinomas) or mammary gland signaling." (PMID 21867536, 2011). "There were no morphological differences in tumor type (solid adenocarcinomas) between bigenic and ErbB2 mammary glands." (PMID 21867536, 2011). "Both tumour sample and HBCx-17 are negative for ERBB2 and oestrogen, and progesteron receptor, and the clinical sample presented a strong EGFR staining that the xenograft did not (data not shown)." (PMID 20877358, 2010). "The tumor was positive for both estrogen receptors (ER) (90%) and progesterone receptors (PR) (70%), negative for human epidermal growth factor receptor 2 (c-erbB-2), and positive for Ki-67 (15%)." (PMID 20478044, 2010). "Tumours with activated ERBB2 signalling via other mechanisms than amplification or over expression will be tested ERBB2-negative." (PMID 20859285, 2010). "The efficacy and safety of combining pertuzumab and trastuzumab in USPC tumours that do not overexpress erbB2 also warrant further investigation." (PMID 19920829, 2010). "HJURP mRNA levels were significantly associated with estrogen receptor (ER), progesterone receptor (PR), Scarff-Bloom-Richardson (SBR) grade, age and Ki67 proliferation indices, but not with pathologic stage, ERBB2, tumor size, or lymph node status." (PMID 20211017, 2010).
tumor (continued). "Compared with ErbB2 low-expressing MDA-MB-435 xenografts, i.p. injected P3-AHNP-STAT3BP preferentially accumulated in 435.eB xenografts, which led to a greater reduction of proliferation and increased apoptosis and targeted inhibition of tumor growth." (PMID 27713313, 2010). "The majority of tumor samples expressed mRNA for EPOR, ERBB2, and IGF1R at varying levels." (PMID 21318160, 2010). "Moreover, within the tumor population expressing nuclear KLF6, it was found that seventy-five percent (21/28) of the cases overexpressed ERBB2." (PMID 20126619, 2010). "Our main approach to identify cancer-related genes was to filter for the most frequent aberrations but we noted that well characterised cancer driver genes, such as CCNE1 and ERBB2, were not identified since they were amplified in less than 40% of tumours." (PMID 20386695, 2010). "None of the 15 known or supposed markers for CTC detection was considered for further investigations either due to detectable expression levels (ERBB2, ESR1, SERPINE1, SERPINE2 and FN1) in healthy controls or due to inadequate gene expression in the tumor cell lines." (PMID 21129172, 2010). "Both methods yielded similar results and showed that ErbB2 overexpression did not enhance tumor growth rate." (PMID 20825649, 2010). "Tumours with very low or no detectable expression of ER can be classified into HER2/ErbB2-positive, normal breast-like and basal-like." (PMID 19826428, 2009). "Only one of the 25 tumours showing negative immunostaining (scored as +1) exhibited ERBB2 amplification." (PMID 19156142, 2009). "The correlation between hCAP18 and ERBB2 expression that was observed in the human tumours did not occur in vitro or in the mouse model." (PMID 19183447, 2009). "While none of the tumours here exhibits amplification of ERBB2, it is surprising to note how poorly represented this frequently amplified cancer gene is on the Illumina platform, although coverage is greater in the latest generation of the array." (PMID 19995423, 2009). "We conclude that while ErbB2 signaling does not seem to significantly modulate eIF2α phosphorylation at Ser51 tumor cells overexpressing this oncogene are highly sensitive to the effects of hyper-phosphorylated eIF2α levels." (PMID 19754954, 2009). "In contrast, β4 was not significantly related to P-Akt, ErbB-2 protein and any conventional pathological parameters, namely tumor size, grading and nodal status." (PMID 18270579, 2008). "Undoubtedly, ErbB2 levels play a significant role in ALM targeting and may explain, at least in part, the lower level of targeting exhibited against MVM2 tumours, as compared with either SK-OV-3 or BT-474 tumours." (PMID 18841159, 2008). "Despite the expression of ErbB3 on the ErbB2‘−’/ErbB3‘+’ MDA-MB-468 tumour model, 125I-ALM failed to accumulate to levels above that seen in blood (0.29±0.07 vs 0.29±0.03% ID per g; P=0.55)." (PMID 18841159, 2008). "The increase in cell motility (P<0.05), which has a major role during the dynamic process of tumour invasion and metastasis, may be a direct result of MUC4-mediated changes in the actin organisation, or indirectly through an ErbB2-mediated pathway." (PMID 18781152, 2008). "Out of seven cancer-associated gene-markers used to detect tumor cells in PBL and BM, CK19, muc1 and ErbB2 were not informative due to the high expression in normal control samples." (PMID 18289390, 2008). "An example of a tumor pair of possibly different origins is tumor pair 2 where one tumor (2b) harbored an ERBB2 amplification, whereas the other (2a) did not." (PMID 18616792, 2008).
tumor (continued). "This is not inconsistent with our previous study of local tumor response in locally advanced BC, most of which did not have ERBB2 amplification, and all of which were treated with neoadjuvant anthracycline-based therapy." (PMID 18702822, 2008). "Therefore, despite their dependence on ERBB2, NIH3T3-HER2 tumours are relatively resistant to trastuzumab." (PMID 18454161, 2008). "It will be interesting to analyse whether similar observations can be made in human tumour cells, whereby analysis of functional ‘ERBB2 dependence’ will be more difficult compared to the NIH3T3-HER2 model." (PMID 18454161, 2008). "Only patients overexpressing ERBB2 are treated with trastuzumab, whereas its use in tumours without ERBB2 expression is useless." (PMID 18454161, 2008). "Microarray studies have shown that basal-like tumors have poor prognosis when compared with ER-positive luminal tumor groups but not when compared with a ERBB2 tumor cluster." (PMID 17263897, 2007). "The expression of the first metagene was significantly elevated in tumours characterised by EGFR/ErbB2 overexpression (median: 1.109) compared to tumours without overexpression of EGFR or ErbB2 (median: 0.909) (P=0.004)." (PMID 17700572, 2007). "In fact, a large subset of patients classified with very favorable outcome shared a common molecular tumor phenotype characterized by ER-positive and/or ERBB2-negative status and low proliferation (low levels of E2F1 as well as BIRC5,TYMS,TOP2A and TK1)." (PMID 17535433, 2007). "Nevertheless, our minimal set of genes allowed us to discriminate the basal, ERBB2, normal-like and luminal subtypes, even though the luminal-type tumours were not tightly clustered but rather spread over several groups." (PMID 17338809, 2007). "Our investigation re-confirmed the prognostic value of elevated P-Akt levels, and demonstrated that P-Akt expression levels are independent of other prognostic parameters, such as tumour size, grading, and node, ER and ErbB-2 status." (PMID 15987444, 2005). "The majority of tumor cells from 78423 R1 were erbB3 negative, although some cells showed weak erbB2 protein expression." (PMID 16168116, 2005). "The prognostic value of Akt phosphorylation is independent of other characteristics, including tumour size and grade, and node, ErbB-2 and ER status." (PMID 15987444, 2005). "Four tumours with increased LRIG1 copy number were analysed by RT-PCR for EGFR/ERBB1, and all four showed significantly lower expression of EGFR/ERBB1 and three showed significantly higher expression of ERBB2 than their matched normal controls." (PMID 16168117, 2005). "HRG stimulation promoted physical and functional erbB2/erbB3 interactions and tumor cell growth, whereas no response to EGF or IGF-1 was observed." (PMID 16168116, 2005). "Whereas all mice vaccinated with Tc-ErbB2/Th-HA liposomes and challenged with ErbB2-expressing cells remained tumour free, none of the Tc-ErbB2/Th-HA vaccinated animals were able to reject challenge with ErbB2 negative but otherwise isogenic tumour cells." (PMID 15812545, 2005). "One of the main finding is that AP-2 transcription factors are probably not involved in the increase in erbB-2 transcript levels in tumours of non-breast origins." (PMID 12942124, 2003). "Since many tumour cells express both ErbB-2 and EGFR and these receptors synergise in cellular transformation, therapeutic reagents simultaneously binding to ErbB-2 and EGFR might offer advantages for tumour therapy." (PMID 8826849, 1996). "However, 20q13 amplification occurred preferentially in stage 3 tumours and MDM2 was correlated to ERBB-2 amplification." (PMID 8980401, 1996).